COQ4 (coenzyme Q4)
Description:
Lyase that catalyzes the C1-decarboxylation of 4-hydroxy-3-methoxy-5-(all-trans-decaprenyl)benzoic acid into 2-methoxy-6-(all-trans-decaprenyl)phenol during ubiquinone biosynthesis.
Synonyms: CGI-92; COQ10D7; SPAX10
Tractability: Antibody: UniProt places it where antibodies can reach, with medium confidence. PROTAC: ubiquitination databases record sites on it; its protein half-life has been measured.
Gene: Protein-coding gene on chromosome 9 (128,322,515 to 128,334,072, forward strand). Ensembl gene ENSG00000167113.
Subcellular location: Mitochondrion inner membrane
Subcellular location (Human Protein Atlas): Mitochondria
Pathways (Reactome):
Metabolism: Ubiquinol biosynthesis
Gene Ontology:
Molecular function: 4-hydroxy-3-methoxy-5-polyprenylbenzoate decarboxylase activity; protein binding; carboxy-lyase activity; zinc ion binding
Biological process: ubiquinone biosynthetic process
Cellular component: mitochondrial inner membrane; mitochondrion; protein-containing complex; ubiquinone biosynthesis complex; extrinsic component of mitochondrial inner membrane
Genetic constraint (gnomAD): Loss-of-function variants: 34 observed, 27.44 expected, observed/expected ratio (o/e) 1.24, 90% interval 0.94 to 1.64. The synonymous counts are far from expectation, so gnomAD's model fits this gene poorly and the ratio says little. Missense variants: 365 observed, 360.61 expected, observed/expected ratio (o/e) 1.01, 90% interval 0.93 to 1.1. Synonymous variants: 197 observed, 158.25 expected, observed/expected ratio (o/e) 1.24, 90% interval 1.11 to 1.4.
Gene-disease validity (ClinGen):
ClinGen rates the evidence that COQ4 causes each of these diseases.
mitochondrial disease (autosomal recessive): Definitive.
Homologues: Orthologues: chimpanzee COQ4 (98% identical), macaque COQ4 (95% identical), mouse Coq4 (82% identical), pig COQ4 (82% identical), dog COQ4 (81% identical), rat Coq4 (80% identical), rabbit COQ4 (80% identical), guinea pig COQ4 (80% identical), tropical clawed frog coq4 (63% identical), zebrafish coq4 (60% identical), Drosophila melanogaster Coq4 (42% identical), Caenorhabditis elegans coq-4 (37% identical).
Diseases named in the same sentence as COQ4 in open-access papers:
COQ4 is named in the same sentence as 38 diseases in open-access papers, as found by Europe PMC text mining. Sharing a sentence is not in itself a finding about the gene and the disease. The quoted sentences say what the papers report.
primary coenzyme Q10 deficiency (5 papers, 2020 to 2024). "Mutations in the COQ2 and COQ4 genes can lead to CoQ deficiency disorders such as multiple system atrophy and primary coenzyme Q10 deficiency, which often result in mitochondrial dysfunction and a wide range of symptoms, including muscle weakness, neurologic abnormalities, and cardiomyopathy." (PMID 38455045, 2024). "Coenzyme Q10 deficiency can result from pathogenic variants in the COQ2, COQ4, COQ6, COQ8A, or COQ8B gene." (PMID 38570878, 2024). "This may be due to the incomplete understanding of the mechanism of how COQ4 gene defects lead to coenzyme Q10 deficiency and why CoQ10 supplementation does not respond well to treatment." (PMID 39398416, 2024). "Moreover, the spectrum of symptoms of encephalopathy, intellectual disability, seizures, and muscle involvement has been described in patients with variants responsible for other primary coenzyme Q10 deficiency (COQ2, COQ4, COQ6, COQ7, COQ9) as well as in patients with COQ8A-ataxia." (PMID 36295857, 2022).
Ataxia (4 papers, 2020 to 2024). Ataxia refers to impaired coordination of voluntary muscle movement. "Cerebellar degeneration has been observed in infants with severe encephalopathy harboring bi-allelic variants in COQ4, and peculiar COQ4-related ataxia phenotypes have been reported." (PMID 38673663, 2024). "A recent report expanded the spectrum phenotype of COQ4 mutations to include childhood-onset spinocerebellar ataxia with stroke-like episodes, associated with a homozygous variant in the COQ4 gene c.230C>T (p.Thr77Ile), reported in two siblings." (PMID 33426503, 2020).
Leigh syndrome (4 papers, 2020 to 2025). A progressive neurological disease defined by specific neuropathological features associating brainstem and basal ganglia lesions. "CES detected likely pathogenic homozygous variants c.370G > A (p.G124S) in the COQ4 gene related to Leigh syndrome." (PMID 39906551, 2024). "PARL is described to affect the assembly of complex III through its substrate TTC19 and to regulate coenzyme Q synthesis through COQ4, causing respiratory chain deficits leading to Leigh syndrome-like neuronal degeneration." (PMID 38182793, 2024). "Moreover, some of the genes that were downregulated in the absence of IRF-5, like Ndufaf3 and Coq4, are associated with mitochondrial disorders in humans and with the Leigh syndrome." (PMID 40494997, 2025).
cardiomyopathy (3 papers, 2022 to 2024). A disease of the heart muscle or myocardium proper. "Mutations in the human COQ4 gene are associated with primary CoQ10 deficiency and with several disease states including a range of neurological afflictions, cardiomyopathy, and respiratory distress." (PMID 36552517, 2022).
Stroke (3 papers, 2020 to 2023). Sudden impairment of blood flow to a part of the brain due to occlusion or rupture of an artery to the brain. "Stroke-like episodes were reported as a potential disease feature of several CoQ10 biosynthesis defects (COQ2, COQ4 and COQ8A)." (PMID 36978966, 2023).
epilepsy (2 papers, 2024). A brain disorder characterized by episodes of abnormally increased neuronal discharge resulting in transient episodes of sensory or motor neurological dysfunction, or psychic dysfunction. "COQ4 mutations have the highest incidence of epilepsy, reaching up to 69%, with a higher prevalence among females." (PMID 39850733, 2024). "The variants in COQ4 could explain epilepsy, brain hypoplasia, and DD." (PMID 39906551, 2024).
astrocytomas (1 paper, 2022). "It was possible that the tendency of upregulated COQ4 level in Grade III astrocytomas was also a response to downregulated CoQ10 levels and that effect was diminished when PDSS2 level was increased or other abnormalities appeared." (PMID 35204836, 2022). "The levels of COQ3, COQ5, COQ6, COQ7, COQ8A, and COQ9, but not of COQ4, were lower in Grade IV astrocytoma tissues than in controls or low-grade (Grades I and II) astrocytomas, but PDSS2 levels were higher in astrocytoma tissues than in controls." (PMID 35204836, 2022).
autosomal recessive cerebellar ataxia (1 paper, 2020). "Finally, a homozygous mutation c.164G>T, p.Gly55Val in COQ4 was reported in two siblings with a combination of slowly progressive ataxia, spasticity, and seizures, constituting an autosomal recessive cerebellar ataxia (ARCA) syndrome." (PMID 33426503, 2020).
Bradycardia (1 paper, 2025). A slower than normal heart rate (in adults, slower than 60 beats per minute). "CoQ4 mutations cause a broad spectrum of mitochondrial disorders, such as bradycardia, respiratory insufficiency, and heart failure associated with CoQ10 deficiency." (PMID 40999338, 2025).
Cerebellar cyst (1 paper, 2023). "Cerebellar hypoplasia and cerebellar cysts are hallmarks of severe COQ4 defects." (PMID 36978966, 2023).
Cerebral atrophy (1 paper, 2020). Atrophy (wasting, decrease in size of cells or tissue) affecting the cerebrum. "Basal ganglion changes and cerebral atrophy were observed on analysing the magnetic resonance imaging (MRI) findings of patients with COQ4 mutations." (PMID 32907636, 2020).
depression (1 paper, 2025). "We further identified a depression-associated pathologicalcascade beginning with elevated Ca2+ levels in hippocampalneurons, which triggers mtO2•–-dependent reductions in Coq4 and elevations in Parkin, driving mitochondrialperipheral fission and reducing synaptic plasticity." (PMID 41169572, 2025).
Hyperglycemia (1 paper, 2025). An increased concentration of glucose in the blood. "Neonatal hyperglycemia has not been reported in any of these cases but has been described for two other Coenzyme Q10 disorders caused by variants in COQ2 and COQ4." (PMID 40062559, 2025).
pancreatic tumor (1 paper, 2023). "However, the role of COQ4, MCRIP2, MRPL50, MRPL14, RFK, and NMNAT3 in pancreatic tumor has not been reported." (PMID 37223030, 2023).
primary coenzyme Q10 deficiency type 7 (1 paper, 2020). "COQ4 is associated with primary coenzyme Q10 deficiency type 7." (PMID 32907636, 2020).
Spastic paraplegia (1 paper, 2024). Complete loss of the ability to move the lower limbs accompanied by spasticity of the lower limbs. "Here, we described three patients with variants in COQ4 gene that primarily presented as childhood or adolescent‐onset spastic paraplegia, in contrast to severe cardiac or neurologic symptoms that develop soon after birth and often result in death." (PMID 38013626, 2024).
mitochondrial disease (2 papers, 2023 to 2024). "COQ4 is the component of the coenzyme Q biosynthetic pathway, the COQ4 mutations might lead to early-onset mitochondrial diseases." (PMID 37223030, 2023). "Homozygous or compound heterozygous variants in COQ4 have been reported to cause primary CoQ10 deficiency‐7 (COQ10D7), which is a mitochondrial disease." (PMID 38013626, 2024).
cancer (1 paper, 2024). A tumor composed of atypical neoplastic, often pleomorphic cells that invade other tissues. "Overall, there was an increase in the TR (e.g., WFDC6, GATS, FMNL3, COQ4, and MEOIC) as the cancer stage progressed, whereas a decrease in the TR was noted for PARVA." (PMID 39349823, 2024).
metabolic disease (1 paper, 2022). A congenital disorder (due to inherited enzyme abnormality) or acquired (due to failure of a metabolically important organ) disorder resulting from an abnormal metabolic process. "Three had potentially treatable metabolic disorders (SLC2A1, COQ4 and SLC6A8)." (PMID 35979408, 2022).
myopathy (1 paper, 2011). A disease of the muscle in which the muscle fibers do not function properly. "Human COQ4 is an interesting candidate gene for patients with CoQ10 deficiency or with developing isolated myopathy with progressive muscle weakness." (PMID 22053791, 2011).
neurodevelopmental disorder (1 paper, 2022). A behavioral and cognitive disorder with onset during the developmental period that involves impaired or aberrant development of intellectual, motor, or social functions. "Five of these genes are already classified as diagnostic grade genes in the IEM panel (COQ4, ELAC2, MRPL44, MSTO1 and SKIV2L) and three others are diagnostic grade genes in different neurology and neurodevelopmental disorder gene panels (EIF2B4, ELP1, EXOSC8)." (PMID 36229886, 2022).
COQ4 also shares sentences with these, for which no sentence is quoted: encephalomyopathy (3 papers); Encephalopathy (2); Intellectual disability (2); cerebellar degeneration (1); Duchenne muscular dystrophy (1); Friedreich ataxia (1); heart failure (1); hereditary optic neuropathy (1); lactic acidosis (1); Lethal congenital contracture syndrome type 3 (1); mitochondrial DNA depletion syndrome 5 (1); multiple system atrophy (1); Nephropathy (1); OXPHOS disease (1); Respiratory distress (1); Respiratory insufficiency (1); X-linked creatine transporter deficiency (1).